XPO1 (exportin 1)
Diseases named in the same sentence as XPO1 in open-access papers (continued):
Sharing a sentence is not in itself a finding about the gene and the disease.
lung carcinoma (20 papers, 2012 to 2025). "XPO1 overexpression has been associated with platinum resistance and inferior prognosis across solid tumors, including lung cancer, by promoting the cytoplasmic mislocalization of critical tumor suppressors and DNA repair regulators." (PMID 41440011, 2025). "The Q626 mutation of XPO1 is second only to the E571 mutation in lung cancer, which is associated with poor prognosis." (PMID 38783482, 2024). "It was previously reported that the primary mechanism underlying XPO1 inhibitor sensitivity of KRAS-mutant lung cancer cell lines was intolerance to nuclear IκBα accumulation, with consequent inhibition of NF-κB signaling." (PMID 35573474, 2022). "A growing body of evidence implicates dysregulation of nuclear-cytoplasmic transport in this process, with XPO1 frequently overexpressed in lung cancers." (PMID 41440011, 2025). "Furthermore, the antitumor efficacy of XPO1 inhibitor selinexor against KRAS-mutant lung cancer patient-derived xenografts (PDX) was recently demonstrated." (PMID 35573474, 2022). "We used immunoblot to examine whether knockdown of TPR alters the expression of proteins involved in NPC functions, and found that XPO1 level was decreased when TPR was knocked down in A549 lung cancer cells." (PMID 34793452, 2021). "XPO1 inhibitors are promising therapeutic strategies in KRAS-mutant lung cancer." (PMID 34299277, 2021). "Lung cancer samples with XPO1 alteration tend to express higher level of NMD3." (PMID 31113936, 2019). "The overexpression of XPO1 has been found in various cancers, including liver, ovarian, pancreatic, gastric and lung carcinomas, and might serve as a potential prognostic indicator." (PMID 31371628, 2019). "The authors went on to demonstrate that inhibition of XPO1 using Selinexor, a clinically-relevant XPO1 inhibitor, prevented NE transformation and prolonged the effects of targeted therapies in both prostate and lung cancer xenograft models of NE transformation." (PMID 39858043, 2025). "Following this, it was discovered that inhibiting Exportin 1 through the downregulation of SOX2 is capable of suppressing NE differentiation in both prostate and lung cancers." (PMID 38543137, 2024). "In this case report, we provide evidence of a novel ALK fusion, XPO1-ALK (intergenic), identified by next-generation DNA sequencing in a patient with advanced lung cancer." (PMID 39911820, 2024). "KPT-185 decreased XPO1 in all tested MCL cells, which is concordant with the previous reports of MCL and lung cancer cells, in which KPT-185 induced proteasomal degradation of XPO1 protein despite its normally long half-life (24 hours)." (PMID 26340096, 2015). "This review explores the role of XPO1 in NSCLC biology and therapy resistance, the rationale for targeting nuclear export, and the current landscape of XPO1-directed clinical development in lung cancer." (PMID 41440011, 2025). "In addition to reporting the identification of a novel ALK fusion, XPO1-ALK (intergenic), and the sensitivity and safety of brigatinib treatment for lung cancer, this study increased the list of known ALK fusion partners in ALK-positive NSCLC." (PMID 39911820, 2024). "Interestingly, it has been reported that KRAS-mutant NSCLC cells are dependent on XPO1-mediated nuclear export, rendering XPO1 a druggable vulnerability in KRAS-mutant lung cancer." (PMID 35573474, 2022). "To test whether NXF1 and XPO1 are exporters of tRNAs in lung cancer cells, we performed RNA immunoprecipitation (RIP) with NXF1 and XPO1 antibodies respectively." (PMID 34793452, 2021). "In lung cancer xenograft models, XPO1 inhibition interfered with NE transformation by downregulating SOX2, a key driver of NSCLC-to-SCLC lineage plasticity, thereby prolonging the efficacy of targeted therapies and supporting XPO1 inhibition as a strategy to constrain NE reprogramming." (PMID 41440011, 2025).
glioma (19 papers, 2014 to 2025). A benign or malignant brain and spinal cord tumor that arises from glial cells (astrocytes, oligodendrocytes, ependymal cells). "The overexpression of XPO1 was also reported in other human cancers such as thymic epithelial tumors, malignant melanoma, osteosarcoma, glioma, ovarian, pancreatic, cervical, colorectal, and gastric cancers." (PMID 40872651, 2025). "XPO1 is upregulated in many malignancies, including pancreatic, ovarian, glioma, lung, gastric, prostate, and colorectal cancers, and is associated with worse prognosis." (PMID 39177040, 2024). "XPO1 is upregulated in pancreatic, ovarian, glioma, lung, gastric, prostate, and colorectal cancers, and these conditions are also linked to a poor prognosis." (PMID 39177040, 2024). "This study aimed to establish a promising predictive tool for glioma prognosis and to distinguish specific patients who can benefit from combinational radiotherapy and XPO1 inhibition." (PMID 32612949, 2020). "This study developed an accurate nomogram based on the combination of radiosensitivity and XPO1 expression for prognosis prediction in glioma patients." (PMID 32612949, 2020). "For glioma patients, XPO1 is a promising treatment modality and is being tested in clinical trials (NCT02323880, NCT01986348)." (PMID 32612949, 2020). "Stratification based on the 31-GS and XPO1 expression status proved to be an independent predictive factor for glioma." (PMID 32612949, 2020). "This study established a prognostic predictor combining a 31-gene signature and XPO1 expression, which stratified glioma cases into four subgroups that were demonstrated with distinct clinical outcomes." (PMID 32612949, 2020). "Since the radiosensitivity signature and XPO1 expression proved to be optimal in predicting the prognosis for glioma patients, a nomogram combining the radiosensitivity signature, XPO1 expression, and clinical characteristics was next generated." (PMID 32612949, 2020). "However, further understanding is required to develop effective clinical XPO1-targeted therapeutic strategies against glioma." (PMID 32612949, 2020). "Glioblastoma (WHO IV) exhibited the highest XPO1 expression levels compared to WHO II and WHO III gliomas in the CGGA cohort." (PMID 32612949, 2020). "The nomogram based on the radiosensitivity gene signature, XPO1 expression, and clinical characteristics performs more optimally compared to the WHO classification and IDH status in predicting survival rates for glioma patients." (PMID 32612949, 2020). "Chromosomal region maintenance 1 (CRM1), also referred to as exportin 1 (XPO1), is a promising therapeutic target for gliomas." (PMID 27733172, 2016). "However, although the expression of circXPO1 was significantly elevated in glioma tissue and cell lines, the levels of XPO1 mRNA were not significantly altered." (PMID 36980172, 2023). "Furthermore, the increased XPO1 expression was not obviously correlated with an advanced stage or shorter survival time in glioma patients." (PMID 36980172, 2023). "Although XPO1 has been established as a potential drug target for malignant glial brain tumors, we still interrogated the TCGA data base for low grade gliomas to assess as to whether or not XPO1 mRNA levels have a prognostic impact on patients with low grade gliomas." (PMID 30337641, 2018).
osteosarcoma (19 papers, 2014 to 2025). A usually aggressive malignant bone-forming mesenchymal neoplasm, predominantly affecting adolescents and young adults. "Canine cancer studies reported the overexpression of XPO1 mRNA levels from patient-derived tissues and cell lines in osteosarcoma." (PMID 40872651, 2025). "In the present study, we sought to characterize the expression of XPO1 in primary canine osteosarcoma (OS) tumour samples, OS cell lines and normal osteoblasts and evaluate the in vitro activity of verdinexor alone or in combination with doxorubicin." (PMID 33438820, 2021). "In osteosarcoma cell lines, XPO1 inhibition decreases hypoxia inducible factor, a key transcriptional regulator of tumor growth and therapy (including radiotherapy) resistance, emphasizing the potential role of selinexor as a radiation sensitizer." (PMID 34944778, 2021). "Similar to most malignant tissues, osteosarcoma shows increased XPO1 protein expression compared with normal tissues, and its expression is associated with worse prognosis, unrelated to important clinical features such as presence of metastatic disease." (PMID 34944778, 2021). "In osteosarcoma, circXPO1 sponges multiple microRNAs, including miR-23a-3p, miR-23b-3p, miR-23c, and miR-130a-5p, to upregulate XPO1 expression, which suggests that circXPO1 facilitates cancer progression by acting as a competing endogenous RNA." (PMID 34386427, 2021). "The efficacy of XPO1 inhibition to reduce osteosarcoma cell growth was next evaluated using the small molecule inhibitor of XPO1, KPT-330 (Selinexor)." (PMID 30992462, 2019). "Studies reported that the expression of XPO1 in both gene and protein in the majority of canine osteosarcoma cells were significantly higher compared with normal canine osteoblast cells, and the XPO1 protein overexpression demonstrated potent activity necessary for cell survival in canine cancers." (PMID 40872651, 2025). "In lung adenocarcinoma and osteosarcoma, circXPO1 expression, which is positively correlated with XPO1 expression, negatively affects patients’ overall survival, thus suggesting that circXPO1 promotes cancer progression and may be used as a potential therapeutic target for cancer treatment." (PMID 34386427, 2021). "Neuroblastoma, osteosarcoma, and high-grade gliomas (HGG) are particularly difficult to treat cancers that affect children, and integration of XPO1 inhibition into therapy has potential to transform management." (PMID 34944778, 2021). "High XPO1 protein expression is correlated with both poor progression-free (PFS) and overall survival (OS) in human osteosarcoma." (PMID 25476752, 2014). "Similar to our results, a study using canine osteosarcoma cells reported that the expression level of XPO1 protein was not directly correlated with sensitivity to KPT-335." (PMID 40872651, 2025). "Since our present findings associate cytoplasmic p27 localization with the metastatic potential of osteosarcoma cells, we evaluated the mRNA levels of the set of metastatic markers, VIM, SNA2, CDH2, CTNNB1 and STMN1 following XPO1 inhibition and AZD1775 exposure, by RT-qPCR." (PMID 30992462, 2019). "XPO1 protein expression is increased in osteosarcoma when compared to non-tumor tissue." (PMID 25476752, 2014).
malaria (18 papers, 2008 to 2025). Malaria is a serious and sometimes fatal disease caused by a parasite that commonly infects a certain type of mosquito which feeds on humans. "IP-MS also revealed that phosphorylated adapter RNA export protein (PHAX) domain-containing protein, an adaptor protein for exportin-1, also interacted with GBP2, implying that mRNA export occurs via the PHAX domain-containing protein pathway in malaria parasites." (PMID 34604117, 2021).
B-cell lymphoma (16 papers, 2017 to 2025). "XPO1 (encoding exportin protein) involvement (Case 16) was demonstrated in primary mediastinal B-cell lymphoma (PMBL) and classical Hodgkin lymphoma (cHL)." (PMID 34204385, 2021). "Almost 25% of patients with either primary mediastinal B-cell lymphoma (PMBL) or classical Hodgkin lymphoma (cHL) possess a recurrent mutation of the XPO1 gene encoding the major nuclear export protein." (PMID 33007990, 2020). "For example, the frequency of XPO1 mutations may reach 50% in primary mediastinal B-cell lymphoma (a rare form of B-cell lymphoma)." (PMID 32924027, 2020). "Overexpression of XPO1 was shown in primary mediastinal B cell lymphomas and classic Hodgkin lymphomas, mantle cell lymphomas, as well as in indolent lymphomas and myeloid neoplasms." (PMID 30266952, 2018). "A recent NGS study of 215 B-cell lymphoma characterized 3 mutated genes: ITPKB, MFHAS1, and XPO1 present in 18 cases (39%, 28%, and 39% respectively) of PMBL." (PMID 27806315, 2017). "In primary mediastinal B‐cell lymphoma (PMBL) and classical Hodgkin's lymphoma (cHL), the XPO1 gene may be mutated on one nucleotide and encodes the mutant XPO1E571K." (PMID 36727672, 2023). "Almost 25% of primary mediastinal B-cell lymphoma (PMBL) and classical Hodgkin lymphoma (cHL) cases harboured a recurrent XPO1 point mutation (NM_003400, chr2:g61718472C>T) resulting in the E571K substitution within the hydrophobic groove of the protein, the site of cargo binding." (PMID 33007990, 2020). "Additionally, studies in B-cell lymphoma and non-small cell lung cancer (NSCLC) indicated that XPO1 mutations may result in resistance to conventional chemotherapy; however, cells with mutated XPO1 demonstrated increased sensitivity to XPO1 inhibitors so that the therapeutic remained effective." (PMID 40872651, 2025). "We evaluated the safety and feasibility of the XPO1 inhibitor, selinexor, in combination with rituximab and RGDP chemotherapy in relapsed/refractory B-cell lymphoma." (PMID 39123400, 2024). "Further, XPO1 inhibition decreased cell fitness in other MYC-driven tumors including human P493-6 Burkitt lymphoma-like, a murine MYC-induced T-cell leukemia and a murine IgH-MYC B-cell lymphoma cell line." (PMID 38302473, 2024).
diffuse large B-cell lymphoma (16 papers, 2017 to 2025). "Increased XPO1 expression is negatively associated with survival in various cancers including diffuse large B cell lymphoma (DLBCL) and mantle cell lymphoma." (PMID 34926302, 2021). "Recent reports have shown molecular alterations in the gene encoding XPO1 and showed a mutation hotspot (E571K) in the following two hematological malignancies with similar phenotypes and natural histories: primary mediastinal diffuse large B cell lymphoma and classical Hodgkin’s lymphoma." (PMID 28196522, 2017). "The exportin 1 (XPO1) selective inhibitor selinexor has been approved by the US FDA for the treatment of relapsed or refractory diffuse large B-cell lymphoma." (PMID 37616529, 2024). "The first-in-class XPO1 inhibitor selinexor has been approved for the treatment of relapsed and refractory multiple myeloma and diffuse large B cell lymphoma (DLBCL) and is currently under clinical evaluation in multiple solid and haematological malignancies." (PMID 36560403, 2022). "Furthermore, the FDA approved selinexor, an XPO1 inhibitor, for MM and refractory diffuse large B‐cell lymphoma." (PMID 38783482, 2024). "Finally, a copy number gain in the XPO1 locus was also observed in patients affected by primary mediastinal B-cell lymphoma (PMBL) and diffuse large B-cell lymphoma (DLBCL)." (PMID 31088931, 2019). "The human XPO1 gene is located on chromosome 2p15, which is close to the c-REL 2p16.1 locus, a locus well known to be gained or amplified in PMBL, germinal B-cell-like (GCB) diffuse large B cell lymphoma (DLBCL), and cHL." (PMID 28196522, 2017).
melanoma (16 papers, 2014 to 2026). A malignant, usually aggressive tumor composed of atypical, neoplastic melanocytes. "Selinexor, a FDA-approved XPO1 inhibitor, has shown antitumor activity in the clinic and is currently being used to treat various human tumors, including melanoma, colon cancer, glioblastoma, and small cell lung cancer." (PMID 38336745, 2024). "Previous studies using human cancer cell lines and canine melanoma cell lines have shown that inhibition of XPO1 with SINE compounds can result in a compensatory upregulation of XPO1 mRNA as a result of XPO1 protein loss." (PMID 33438820, 2021). "While protein was decreased, messenger RNA for XPO1 was increased in the canine melanoma lines following KPT-335 exposure, a finding also observed in human cell lines treated with the SINE compounds." (PMID 25022346, 2014). "Our mechanistic findings show that SINE XPO1 antagonists induce antitumor activity against melanoma via effects upon cell growth and apoptosis." (PMID 25057921, 2014). "Inhibition of XPO1 using SINE represents a potential therapeutic approach for melanoma across cells with diverse molecular phenotypes by promoting growth inhibition and apoptosis." (PMID 25057921, 2014). "Concordant with results in human cell lines, XPO1 mRNA was similarly upregulated in the melanoma cells following incubation with KPT-335 for 24 hours, demonstrating a compensatory response to loss of XPO1 protein." (PMID 25022346, 2014). "XPO1 inhibition represents one potential approach to targeting melanoma cells of heterogeneous genotypes." (PMID 25057921, 2014). "Downregulation of XPO1 protein was observed in melanoma cell lines as early as 4 hours after drug exposure and expression was nearly completely eliminated by 24 hours of treatment." (PMID 25022346, 2014). "The known association of these growth regulatory proteins with XPO1 prompted us to first examine how inhibition of XPO1 would alter melanoma cell growth." (PMID 25057921, 2014). "The non-drug-like, natural product leptomycin B (LMB) has been used to potently inhibit XPO1 function and induce anti-proliferative activity in a range of tumor cell lines, including melanoma." (PMID 25057921, 2014). "Selective inhibitor of nuclear export (SINE) compounds that target the nuclear export protein XPO1 represent a potential target for therapeutic intervention in canine and human melanoma." (PMID 25022346, 2014). "Together these data suggest that XPO1 inhibition is worthy of further investigation in the setting of advanced melanoma." (PMID 25057921, 2014). "In summary, KPT-335 (verdinexor), a novel orally bioavailable XPO1 inhibitor exhibits good in vitro single agent activity against canine malignant melanoma cell lines as evidenced by inhibition of proliferation and induction of apoptosis." (PMID 25022346, 2014). "XPO1 transcript was elevated in all cell lines at both concentrations of verdinexor consistent with a compensatory response to XPO1 inhibition, a finding similarly seen in canine melanoma cells." (PMID 33438820, 2021). "Recent studies also implicate that XPO1 inhibitors may synergize with BRAF inhibition in human melanoma cell lines, supporting the concept that nuclear export inhibition may play a role as a therapeutic strategy for this disease." (PMID 25057921, 2014). "In addition, novel small molecule inhibitors of XPO1-mediated nuclear export displayed potent anti-proliferative and pro-apoptotic effects on human melanoma cell lines." (PMID 25057921, 2014). "We investigated whether XPO1 is a potential therapeutic target in melanoma using novel selective inhibitors of nuclear export (SINE)." (PMID 25057921, 2014).
melanoma (continued). "Therefore we hypothesized that inhibition of XPO1 in human melanoma cells would induce nuclear retention of key proteins that promote tumor suppressive pathways and inhibit melanoma cell viability." (PMID 25057921, 2014). "Finally another recent report suggests XPO1 inhibitors may synergize with BRAF inhibitors to elicit antitumor effects against melanoma." (PMID 25057921, 2014). "The most promising results seem to come from the novel orally bio-available XPO1 (selective inhibitor of nuclear export)-inhibitor KPT-335, which has demonstrated biological activity against canine melanoma cell lines at physiologically relevant doses." (PMID 39408717, 2024). "Inhibition of XPO1 using KPT-185, -251, -276, and -330 impaired melanoma survival in both BRAF mutant and wild-type melanoma cell lines and in mouse xenografts." (PMID 24503695, 2014). "Moreover, there are pieces of evidence of potential synergy between XPO1 and BRAF inhibition in BRAF-mutant melanoma, but this needs to be further investigated in a clinical setting." (PMID 34575598, 2021).